ZSCAN23 (zinc finger and SCAN domain containing 23)
Description:
May be involved in transcriptional regulation.
Synonyms: ZNF390; ZNF453; dJ29K1.3.1; dJ29K1.3
Tractability: No criterion of Open Targets' tractability assessment is met for any kind of drug.
Gene: Protein-coding gene on chromosome 6 (28,425,321 to 28,443,502, reverse strand). Ensembl gene ENSG00000187987.
Subcellular location: Nucleus
Subcellular location (Human Protein Atlas): Nuclear speckles; Golgi apparatus
Gene Ontology:
Molecular function: protein binding; sequence-specific double-stranded DNA binding; DNA-binding transcription factor activity, RNA polymerase II-specific; RNA polymerase II cis-regulatory region sequence-specific DNA binding
Biological process: regulation of transcription by RNA polymerase II
Cellular component: nucleus
Genetic constraint (gnomAD): Loss-of-function variants: 20 observed, 21.51 expected, observed/expected ratio (o/e) 0.93, 90% interval 0.65 to 1.35. The upper end of that interval is the gene's LOEUF score, 1.35, which puts it in group 5 of 6, group 1 being the genes least tolerant of losing a copy. Missense variants: 372 observed, 465.01 expected, observed/expected ratio (o/e) 0.8, 90% interval 0.73 to 0.87. Synonymous variants: 140 observed, 167.9 expected, observed/expected ratio (o/e) 0.83, 90% interval 0.73 to 0.96.
Homologues: Orthologues: chimpanzee ZSCAN23 (99% identical), macaque ZSCAN23 (96% identical), pig ZSCAN23 (84% identical), rabbit ZSCAN23 (78% identical), dog ZSCAN23 (77% identical). Paralogues in human: ZSCAN12 (56% identical), ZSCAN9 (51% identical), ZSCAN31 (51% identical), ZSCAN30 (50% identical), ZNF397 (50% identical), ZKSCAN3 (48% identical), ZKSCAN8 (48% identical), ZSCAN21 (47% identical), ZKSCAN4 (47% identical), ZNF165 (47% identical), ZNF24 (46% identical), ZKSCAN1 (46% identical), and 18 more.
Diseases named in the same sentence as ZSCAN23 in open-access papers:
ZSCAN23 is named in the same sentence as 7 diseases in open-access papers, as found by Europe PMC text mining. Sharing a sentence is not in itself a finding about the gene and the disease. The quoted sentences say what the papers report.
epilepsy (1 paper, 2026). A brain disorder characterized by episodes of abnormally increased neuronal discharge resulting in transient episodes of sensory or motor neurological dysfunction, or psychic dysfunction. "Nine shared genetic loci and six pleiotropic genes, including SCN1A, PGBD1, ZKSCAN3, ZKSCAN4, VRK2, and ZSCAN23, have been identified between epilepsy and psychiatric disorders." (PMID 41733899, 2026).
glioma (1 paper, 2024). A benign or malignant brain and spinal cord tumor that arises from glial cells (astrocytes, oligodendrocytes, ependymal cells). "Summarizing the MR results presented in the heatmap, we observed that SRA1, SCDF1, SLC25A24, ZSCAN23, and ZSCAN26 were notably associated with glioma risk across at least two cell types, with consistent MR estimates, indicating potential cross‐cell effects of these genes." (PMID 39722126, 2024).
pancreatic cancer (1 paper, 2025). "Promoter region hypermethylation of ZSCAN23 has been associated with the acceleration of pancreatic cancer growth." (PMID 40051167, 2025).
cancer (5 papers, 2017 to 2025). A tumor composed of atypical neoplastic, often pleomorphic cells that invade other tissues. "Combined with the common ZSCAN23 locus we identified, associated with pancreatic tumors, this points to cancer being the major genetic factor currently affecting lifespan in UKB." (PMID 39132489, 2024). "For instance, NOVA1, NRXN1, TMEM132C, USP44, VIPR2, and ZSCAN23 were consistently downregulated in nine cancers." (PMID 28060724, 2017). "Consequently, we conducted a pan-cancer analysis of gene promoter methylation and observed significant associations between several genes, including ZNF323, ZSCAN23, SCAND3, PRSS16, ZNF391, NKAPL, and ZNF311, and promoter methylation." (PMID 38495498, 2024).
tumor (1 paper, 2021). "Respectively, the expression of CDO1, CELF2, ITPRIPL1, KCNH8, RIC3, USP44 and ZSCAN23 was significantly lower in tumor tissues, whereas the expression of PTK6 and RAB25 was significantly higher in tumor tissues." (PMID 34056873, 2021).
ZSCAN23 also shares sentences with these, for which no sentence is quoted: psychiatric disorder (1 paper); schizophrenia (1).